ENSG00000201009
Synonyms: LOC124900236
Gene: Small nucleolar RNA gene on chromosome 7 (132,753,023 to 132,753,126, forward strand). Ensembl gene ENSG00000201009.
Gene Ontology:
Biological process: RNA processing
Cellular component: nucleolus
Homologues: Orthologues: zebrafish SNORD46 (64% identical). Paralogues in human: SNORD46 (86% identical).